FLT3 (fms related receptor tyrosine kinase 3)
Diseases named in the same sentence as FLT3 in open-access papers (continued):
Sharing a sentence is not in itself a finding about the gene and the disease.
cancer (continued). "Our results open new perspectives for the study of translation dynamics and therapy resistance in cancer and suggest the clinical evaluation of combined FLT3 and autophagy inhibition to overcome primary treatment resistance against FLT3-targeted therapy and improve its efficacy." (PMID 35999260, 2022). "They demonstrated that the anti-FLT3 CAR-R2 T-cells could eradicate the cancer cells and that the CAR T-cells were partially depleted when rituximab was administered." (PMID 36289703, 2022). "The perturbational class identified in our study, namely PI3K inhibitors, mTOR inhibitors, IGF-1 inhibitors, JAK inhibitors, DNA dependent protein kinase inhibitors, HDAC inhibitors, and FLT3 inhibitors, were also reported to mediate immune modulation in various cancers." (PMID 35954379, 2022). "In FLT3-ITD AML, HHT induces cancer cell apoptosis through inhibiting the FLT3-AKT-c-Myc pathway." (PMID 34681590, 2021). "AXL/ALK/FLT3 inhibitors (e.g., gilteritinib) have shown promise as anti-cancer agents." (PMID 33917370, 2021). "Herein, we will review the current evidence which suggests that the stimulation of DCs through the Flt3/Flt3L axis may contribute to improved cancer immunotherapy." (PMID 33810248, 2021). "Recently, given that aberrant activation of Fms-like tyrosine receptor kinase 3 (FLT3) acts as a critical survival signal for cancer cells in 20‒30% patients with AML, inhibition of FLT3 may be a potential therapeutic strategy." (PMID 33391463, 2021). "In particular, MEIS1, FLT3, TNF, PBK, and IGF2BP, all associated with cancer, were down-regulated." (PMID 32698374, 2020). "To verify the presence of FLT3 mutations and also in order to see whether any other oncogenic mutations exist in RS4;11 cells, we used targeted sequencing of 600 cancer-related genes." (PMID 30962949, 2019). "Most genes from the “Pathways in cancer” (FLT3, IGF1R, DAPK2, PLD1 and MMP9) are inhibited due to the action of BE resulting in an anti-proliferative and pro-apoptotic action of the combined therapy, with the notable exception of the up-regulation of the apoptosis inhibitor BIRC3." (PMID 28359318, 2017). "An unexpected result of the cancer hotspot panel sequencing approach was the identification of mutations in genes usually associated with non-epithelial malignancies, such as IDH1 R132H/R132C, JAK3 V722I, and FLT3 A680V." (PMID 25656989, 2015). "Though there are have been additional effectors known downstream of both Mer and Flt3 in various cell types, we chose to analyze these molecules which function to promote cancer cell growth and prevent apoptosis and have well-characterized roles in leukemogenesis." (PMID 25762638, 2015). "Understanding the network of enzymes that FLT3 works with could therefore help researchers to develop more effective and safer cancer treatments." (PMID 25531068, 2014). "Notably, genetic testing to guide cancer treatment, e.g., by assessing mutations in EFGR, KRAS, FLT3 and NPM is already established in other cancers." (PMID 23750322, 2012). "The crystal structures of FLT3, KIT and MET kinases have suggested that cancer mutations may destabilize the autoinhibited wild-type (WT) form." (PMID 19834613, 2009). "There are examples of cancer mutations displaying a subgroup level of conservation, including EGFR-L858 position, which bears a conserved leucine in EGFR and ABL kinases, or a conserved aspartate shared in FLT3, KIT, MET, PDGFRα." (PMID 19834613, 2009). "So, Sunitinib was not approved for AML or other mutated FLT3-expressing cancer types." (PMID 37438819, 2023).
cancer (continued). "CDKN2A, IKZF1, ETV6, RUNX1, and FLT3 were the top genes mutated in leukemias, while somatic alterations in ALK, NF1, and PTEN primarily occurred in solid tumors, suggesting that the driver alterations are either common to cancer (e.g., cell cycle) or specific to pediatric cancer histotype." (PMID 36845394, 2023). "Previous studies demonstrated that USP10 could deubiquitinate and stabilize Yes-associated protein (YAP)/PDZ-binding motif (TAZ), HDAC6, FMS-like tyrosine kinase 3 (FLT3), spleen tyrosine kinase (SYK) and topoisomerase Iiα (TOP2α), thus promoting cancer progression." (PMID 36163081, 2022). "In addition, the cancer may become refractory to chemotherapy, leaving FLT3-inhibitors such as gilteritinib or quizartinib the only treatment option." (PMID 33832508, 2021). "Besides, quercetin could inhibit the activities of many kinases implicated in cancer cell biology, such as ABL1, Aurora-A, -B, -C, CLK1, FLT3, JAK3, and MET." (PMID 31998395, 2019). "Alternative signalling pathways could not, however, restore cancer growth signals (proliferation and loss of apoptosis) to the same levels as prior to treatment, which may explain why FLT3 resistance mutations are the most common resistance mechanism." (PMID 29699481, 2018). "However, a recent study revealed that P22077 and HBX19818 may also inhibit the deubiquitinase activity of USP10 and induce the proliferation inhibition of mutant-FLT3 (FLT3-ITD)-positive cancer cells." (PMID 30319415, 2018). "Crenolanib is known to potently inhibit mutant-FLT3 D835 and -PDGFR D842 isoforms in vitro and is currently being investigated in several clinical trials for the treatment of FLT3 D835- and PDGFR D842-associated cancers, (clinicaltrials.gov; e.g. NCT01243346, NCT01522469, NCT02400281)." (PMID 29137311, 2017). "Therefore, MV4-11 AML cancer cell line, a FLT3-positive cell line which exhibits multidrug resistance, was included in our experimental system to investigate the mechanism of ADR’s anticancer activity, especially ADR’s effect on multidrug resistant cancer cells." (PMID 28858244, 2017). "Similarly, in a Cancer and Leukemia Group B study, which included 196 adult AML patients from two clinical studies, WT1 mutation predicted a worse 3-year disease-free and OS compared to wild-type WT1 AML patients independently of CEBPA, FLT3-ITD, and NPM1 mutational status." (PMID 41102401, 2026). "Unbiased clustering using UMAP identified several cell types, including KRT19+ cancer cells, CD3E+ T cells, MS4A1+ B cells, MZB1+ plasmablasts, FLT3+ dendritic cells (DCs), and PROX1+ LECs, which were then visualized within the tissue context." (PMID 41249124, 2025). "A database analysis revealed a strong positive correlation between FLT3 and NLRP3 in cancer, which was particularly evident in AML patients." (PMID 39875995, 2025). "New drugs have recently been developed which act on genes necessary for AML cancer cell survival, such as FMS-like tyrosine kinase 3 (FLT3) and isocitrate dehydrogenase (IDH) 1/2 inhibitors." (PMID 40153395, 2025). "Strikingly, the co-expression of NLRP3 and FLT3 is exceptionally pronounced in AML, exceeding the levels observed in all other investigated cancer types." (PMID 39875995, 2025). "PI3K/AKT reactivation has been observed as an adaptive response in other cancers, but further investigation is required to determine if AKT reactivation is an adaptive response in FLT3/ITD AML." (PMID 39395205, 2025). "As 5-3 was designed based on plinubulin, which inhibits cancer cell growth by targeting β-tubulin, we conducted molecular docking of 5-3 with β-tubulin (PDB: 4XHC) to determine if its potency in killing FLT3-ITD mutant cells is related to β-tubulin." (PMID 40710514, 2025). "These include FLT3 in FLT3-ITD positive cells, DOT1L in PICALM-MLLT10, and the oncogene c-MYC, which is overactive in most cancer types." (PMID 40082888, 2025).
cancer (continued). "The FLT3 and MYCN genes are critical in the transcriptional misregulation pathway in cancer, with FLT3 functioning in signal mediation." (PMID 40911615, 2025). "Recent studies have reported that RTKs other than KIT, such as FLT3-ITD, PDGFRA, MET, and insulin-like growth factor receptor 1 (IGF-1R), also use the Golgi/TGN as their signaling platform in cancer cells." (PMID 38679330, 2024). "Compound F08060425 affects key pathways like cytokine signaling and the Adaptive immune system, interacting with genes FLT3, SYK, and ROCK1, indicating its role in immune modulation and potential applications in cancer therapy." (PMID 39286631, 2024). "Although the discovery of mutant oncoproteins such as FLT-3 ITD, BCR-ABL, and IDH have offered clinically relevant cancer-specific targets; in most cases, cancer metabolic reprograming involves alterations of pathways that occur in nonmalignant cells." (PMID 36634302, 2023). "In NCI-60 cancer cell lines, we observed different effects on GDF15 expression for the two FLT3 inhibitors sorafenib and sunitinib." (PMID 37495707, 2023). "Cenisertib inhibits the kinase activity of AKT as well as FLT3, VEGFR2, LYN, BTK, and KIT and promotes growth inhibition, cell cycle arrest, and apoptosis in many cancer cell lines." (PMID 36590916, 2022). "Across non-cancer hematopoietic cells, the interaction between DS2 and DS1 elements mainly control FLT3 gene for partition into 2 TADs, where DS3 is positioned over a closer TAD and DS2 element intersects with the TAD boundary." (PMID 35397520, 2022). "EGFR, HER2, ALK, AXL, FLT3, PDGFR and other receptors and signal transducers (e.g., Raf) are involved in the metastasis of various cancers." (PMID 35477123, 2022). "The function of 6 NRGs in our signature, including FASLG, IPMK, FLT3, SLC39A7, HSP90AA1, and LEF1, are studied in various cancer types, including BC." (PMID 35864548, 2022). "Altogether, our data point to subunits of the 19S proteasome as novel prognostic biomarkers and putative targets for therapy in FLT3+ AML, CML, and other types of cancers that are worthy of future investigation." (PMID 36498916, 2022). "Sunitinib inhibits PDGFRs, VEGFRs, c-kit, FLT3, CSF-1R and RET and is FDA approved for the treatment of several cancers." (PMID 35629326, 2022). "Higher expression of FLT3 results in poor overall survival (OS) in AML patients, as seen in the cancer genome atlas (TCGA) dataset analyzed by GEPIA." (PMID 35267471, 2022). "AXL, a member of the TAM receptor family, is strongly activated in many different cancer types and was shown to drive resistance of AML cells to FLT3 inhibitors via signals from the stromal microenvironment and the activation of STAT5." (PMID 34944800, 2021). "Next to being overexpressed in many cancers, MERTK and FLT3 have important roles in immune cell development and function." (PMID 34835225, 2021). "In the Children’s Cancer Group (CCG) study, FLT3-ITD was present in 77 of the 360 tested patients (12%), and in the study performed by the AML-BFM Study Group, this mutation was found in 52 out of the 353 analyzed patients (15%)." (PMID 34572762, 2021). "For example, targeting the PI3k-Akt signaling pathway results in an anti-leukemic effect by activating oncogenes upstream (FLT3-ITD, KIT, NRAS, etc.); and dysregulated Ca2+ homeostasis plays a crucial role in the pathogenesis of various cancers." (PMID 33926391, 2021).
cancer (continued). "AT13387 exerted high activity against cancer cells addicted to several oncoproteins including receptor tyrosine kinases such as EGFR, ERBB2, c-MET (hepatocyte growth factor receptor) and FLT3 (Fms-related tyrosine kinase 3)." (PMID 31659567, 2020). "In 2006, 19% of FLT3POS cases (FLT3–ITD with 12% and FLT3-TKD with 6.7%) were detected in a group of 630 de novo AML pediatric patients, belonging to the Children's Cancer Group." (PMID 33042924, 2020). "For mutant FLT3‐positive AML patients to achieve maximum clinical benefit, it has been imperative that midostaurin be administered in combination with other anti‐cancer agents." (PMID 31943762, 2020). "Thus, its molecular pattern can be exploited synthetically at different positions, especially at X, Y, W, and Z, and may aid in the search for new indolin−2-one derivatives with dual Aurora B/FLT3 activity that may become drugs used in the treatment of different types of cancer in the future." (PMID 32283751, 2020). "Furthermore, IAF79 can be considered to be a promising dual Aurora B/FLT3 inhibitor, and its molecular pattern can be exploited synthetically to search for new indolin−2-one derivatives that may become drugs used in the treatment of cancers, including AML." (PMID 32283751, 2020). "Compound 8t showed potent anti-proliferative activity against a variety of cancer cell lines including MV4-11 cells, and inhibited phosphorylation of CDK and FLT3 pathways in a dose-dependent manner." (PMID 31731727, 2019). "The downregulated genes were associated with cell cycle, TGF-β signaling, FoxO signaling, HIF-1 signaling, and cancer (CDKN1B, FLT3, PDK1, FOXO1, BCL2, ERG), suggesting potential positive regulation of these pathways by SHARP1 to maintain MLL-AF6 AML activity." (PMID 29692408, 2018). "We previously showed that the efficacy of binase against cancer cells was dependent on the expression levels of oncogenic proteins such as cKIT, AML1-ETO, FLT3 and RAS." (PMID 29069817, 2017). "Cancer cell lines dependent on known receptor tyrosine kinases (such as EGFR, ERBB2, c-MET, and FLT3) were found to be sensitive to SHP2 depletion." (PMID 29371942, 2017). "Oxidative stress has been found in many cancers, including hematologic malignancies and elevated ROS levels have been detected in hematopoietic cells transformed by JAK2V617F, FLT3-ITD and Bcr-Abl oncogenes." (PMID 27566554, 2017). "We have been involved in the development of kinase inhibitors as targeted anti-cancer agents and have reported series of compounds based on furanopyrimidine and quinazoline cores as potential AURK/FLT3 inhibitors." (PMID 27863392, 2016). "Inhibition of FLT3 resulted in blockage of FLT3 and STAT5 phosphorylation and triggered apoptosis in cancer cells relying on FLT3 signalling for survival." (PMID 22187040, 2012). "While JAK2 mutation is a common means to stimulate oncogenic STAT activity, perturbations in other signaling networks, such as those mediated by EGFR, IL-6/IL-6R or FLT3, can also contribute to activated STAT signaling in cancer cells." (PMID 21533169, 2011). "Thus, we first analyzed the co-expression profiles of FLT3 and NLRP3 using the TCGA Pan-Cancer data via UCSC Xena." (PMID 39875995, 2025). "Furthermore, there remains a need for reliable biomarkers of NRF2 inhibition across cancer types, with recent data suggesting that HO-1 expression or downstream redox parameters such as ROS levels or glutathione (GSH/GSSG) ratios may serve as useful indicators in FLT3-mutated AML." (PMID 41003134, 2025). "Independent of the cancer type, there is a significant positive correlation between FLT3 and NLRP3 expression." (PMID 39875995, 2025).
cancer (continued). "In conclusion, our study has elucidated the expression profile of CD80 in FLT3-ITD AML cells and proposed a hitherto unrecognized hypothesis that ROS drives CD80 expression as a regulator of the cancer cell adaptive response." (PMID 40746567, 2025). "Gilteritinib, a second-generation type I inhibitor, was not available in the Genomics of Drug Sensitivity in Cancer database, but had a reported IC50 value of approximately 1.5-12 nM for cells with various FLT3 mutations and wild-type FLT3." (PMID 41287669, 2025). "In addition, this study found that DEGs in the three groups were also enriched in cancer and certain disease pathways (TNFSF10, ACKR4, FLT3, SIGLEC1, etc.)." (PMID 40282783, 2025). "Additionally, the MV4-11 human AML cell line contains mutant FLT3-ITD and expresses the MLL-AF4 fusion protein common in AML cancer." (PMID 38399263, 2024). "Although inhibitors to Ras/MAPK signaling, including BRAF V600E and KRAS G12C inhibitors, are approved for other cancers, the Ras/MAPK pathway mutations observed in resistance to FLT3 inhibitors are not sensitive to these agents." (PMID 38112995, 2024). "FLT3 and HCK are described as attractive targets for cancer therapy." (PMID 38491064, 2024). "Whereas FLT3-ITD is an unfavorable mutation in AML and the proven cause of this cancer, FLT3-TKD is not linked to worse patients prognosis." (PMID 39300221, 2024). "FLT3 is mainly observed in cancer epithelial and myeloid cells, with minimal expression in normal epithelial cells." (PMID 39512680, 2024). "Sorafenib-acquired resistance reportedly involves a variety of mechanisms, including multiple-signal pathway crosstalk; abnormal expression of tyrosine kinase receptors, such as PDGFR- β, c-kit, Flt-3, VEGFR and EGFR; epithelial-mesenchymal transition (EMT); and cancer stem-cell differentiation." (PMID 36698167, 2023). "STAT5 inhibitors have been used to abrogate the constitutive activation of STAT5 signaling in cancer, and tyrosine kinase inhibitors (TKIs) that target the upstream signaling molecules of STAT5 — such as JAK, FLT3, and BCR-ABL — have been shown to be effective in clinical settings." (PMID 36927693, 2023). "The finding that Gilteritinib decreased Myc protein expression suggests that FLT3 may contribute to SORE6 activity and cancer stemness by upregulating Myc." (PMID 38203669, 2023). "For example, targeting PI3K–Akt signal pathway to produce antileukemia effect is to use it to activate upstream oncogenes (such as Flt3–ITD, KIT, and NRAS), and calcium homeostasis disorder plays an important role in the pathogenesis of different kinds of malignant tumors." (PMID 36452344, 2022). "Therefore, it is expected that CT053PTSA will have exhibit performance in cancer patients with MET, AXL, VEGFR-2 and FLT3 overexpression." (PMID 36341335, 2022). "Remarkably, IL7R, FLT3, C1QC, and HLA-DRB5 were all negatively correlated with cancer purity." (PMID 35300397, 2022). "Flt3L/Flt3 is an essential pathway for DC development and function, although its potential in cancer immunotherapy is not yet clearly established." (PMID 33810248, 2021). "Since STAT5 activation in the various cancers is dependent on the phosphorylation by various tyrosine kinases, for example JAK2, Bcr-Abl, Flt3 and Src, targeting the tyrosine kinases to inhibit the activation of STAT5 is a feasible way of treating cancers dependent on STAT5 signalling." (PMID 32872372, 2020). "The constitutive activation of STAT5 signalling in cancer can be abrogated by STAT5 inhibitors or tyrosine kinase inhibitors (TKIs) that target the upstream signalling molecules, such as JAK, Flt3 and Bcr-Abl." (PMID 32872372, 2020). "L-carnitine, responsible for fatty acid transportation across the mitochondrial membrane, was considerably higher in FLT3-ITD, a result which is in line with other reports on different types of cancer and that indicates carnitine as a potential useful biomarker in pediatric AML with FLT3-ITD." (PMID 32872391, 2020).